PIK3CA (phosphatidylinositol-4,5-bisphosphate 3-kinase catalytic subunit alpha)
Diseases named in the same sentence as PIK3CA in open-access papers (continued):
Sharing a sentence is not in itself a finding about the gene and the disease.
cancer (continued). "This showed that PIK3CA and PTEN could significantly co-occur in pan-cancer cell lines (p = <0.001) and tumors (p = <0.001)." (PMID 31289610, 2019). "We also performed individual network analysis and found that PIK3CA and PTEN could strongly interact and this was consistent with our data as it co-occurred significantly in pan-cancer cell lines and tumors." (PMID 31289610, 2019). "It is possible that genetic PIK3CA-activation, due to its constitutive signalling (as opposed to transient PI3K signalling upon growth factor stimulation), leads to a deregulation of cell biological processes in such a way that these become cancer-promoting." (PMID 31374965, 2019). "Interestingly, the presence of PIK3CA mutations is associated with better treatment response to PI3K/AKT/mTOR pathway inhibitors, suggesting that this genetic alteration may serve as a marker for personalized medicine in order to predict treatment outcomes for this cancer entity." (PMID 31058807, 2019). "In contrast, PIK3CA depletion did not affect PI3K signaling and cell growth in PTEN-deficient cancer cell lines." (PMID 29596304, 2018). "Interestingly, rDriver assigned lower ranks to PIK3CA E545K in GBM and in KIRC than in other cancer types, consistently with the observed CCF patterns." (PMID 29738578, 2018). "We found that according to the KEGG enrichment of the common DEGs deregulated upon SOX2OT inhibition; the pathways related to cancer (Kegg: 05200) is one of the most significant enriched pathway (p-value = 0.009285) with 6 genes (HIF1A, HRAS, CHUK, PIK3CA, CDK2, VHL)." (PMID 30202240, 2018). "Class IA PI3Ks (PIK3CA, PIK3CB, and PIK3CD) are the most important isoforms in cancer." (PMID 29642462, 2018). "Two out of six mutations (PIK3CA H1047R and KRAS G12C) was associated with sensitivity in either the cancer-type-specific or the non-specific setting." (PMID 30053901, 2018). "Another 44 studies did not report patient survival, 51 focused on components of the PI3K/AKT pathway other than PIK3CA, and 19 did not examine PIK3CA expression in cancer tissues." (PMID 29484141, 2018). "Like MMP2, PIK3CA and AKT1 play important roles in cancer cell migration and metastasis." (PMID 29322935, 2017). "Co-treatment with both drugs resulted in significant synergistic decrease in cell viability in Caski and T47D cells, but no synergism was observed in the other PIK3CA-mutant cancer cells." (PMID 28036259, 2017). "In this study, we showed that the PIK3CA mutant cell line MFE-280 reached an SF50 of 10 μM in cell viability assay and was the only cancer cell line where TGX-221 induced cell death, albeit weakly, and only at the highest dose at 10 μM, hence with low efficacy." (PMID 28002804, 2017). "In addition, PIK3CA.E542K, PTPN11.G268S, AKT1E17K and APC.T1556Nfs*3 were also observed in multiple cancer types." (PMID 29038591, 2017). "Further, A3 deaminase activity is causally associated with helical domain hotspot mutations in the phosphatidylinositol-4,5-bisphosphate 3-kinase catalytic subunit alpha (PIK3CA) gene, which are more prevalent in HPV-positive cancers when compared to HPV-negative cancers." (PMID 28825669, 2017). "We validate the gene activity score using data from the Cancer Cell Line Encyclopedia and drug sensitivity data for five compounds: BYL719 (PIK3CA inhibitor), PLX4720 (BRAF inhibitor), AZD6244 (MEK inhibitor), Erlotinib (EGFR inhibitor), and Nutlin-3 (MDM2 inhibitor)." (PMID 26864072, 2016). "In patient P4, two of four malignant ascites-emerging clones may be targetable by inhibitors against BRAF (e.g. Vemurafenib), TEP1, ERBB4, PIK3CA, HDAC9, or FYN." (PMID 26811494, 2016).
cancer (continued). "Thus both PIK3CA and PDK1, as well as p-AKT, were potential drug targets in ARID1A-mutant cancer cells." (PMID 27323812, 2016). "No significant equivalent sensitivity was noted for other cancer metabolic drugs such as PIK3CA (GDC0941 and AZD6482), GSK3A/B (SB 216763) inhibitors and PRKAA2 (AICAR and metformin) agonists." (PMID 24699711, 2014). "Effects of RAF, MEK, and RAF/MEK inhibitors on cancer cell lines with or without RAS, BRAF, PIK3CA, or PTEN mutations." (PMID 25422890, 2014). "For example, in our study HRAS (P = 5.0 × 10-46), AKT1 (P = 9.5 × 10-26), PIK3CA (P = 5.5 × 10-5), B2M (P = 6.7 × 10-4), and KDM5C (P = 3.5 × 10-3) were predicted to be putative cancer genes using Fisher’s exact test and evidently designated as cancer driver genes according to the 20/20 rule." (PMID 25360158, 2014). "In addition to known cancer driver genes such as ERBB2 (6% of cases), NRAS (3%), MET (3%), PIK3CA (1%), AKT2 (1%), TSC1 (1%), and ERBB4 (1%), several putative cancer genes were identified, such as PTPRC, SYNE2, GRIN2A, and CDH10." (PMID 24576404, 2014). "Importantly, we found Ki67 levels to be independent of PIK3CA mutation status or other alterations in the pathway, suggesting that selecting cohorts of patients based on pathway activation would not necessarily identify low risk patients with non-proliferative cancers." (PMID 24520381, 2014). "In the responsive group, 9 mutations (26%) were found in genes concerning proliferation pathways: PIK3CA (2 ADC with exon 9 E545K, and a poorly differentiated carcinoma with H1047R), BRAF (V600E in 2 ADC), STK11 (V197fs 69 in one ADC and F354L in one SCC), NTRK2 (L755L in a SCC) and MET (N375S)." (PMID 25561229, 2014). "Some, but not all, reports have concluded that PIK3CA mutations and PTEN loss are mutually exclusive in breast and other cancers 26–42." (PMID 24156022, 2013). "Despite these differences, there were significant overlaps in the mutational profiles of the two cancer types, including mutations in the NOTCH receptors (NOTCH1-3), HRAS, and PIK3CA that were seen in both HPV-positive and negative disease." (PMID 23663293, 2013). "In addition to canonical PIK3CA/PTEN genetic alterations, the increased activation of the PAM pathway in cancer cells can be caused by other genetic and non-genetic factors." (PMID 40565304, 2025). "Recent sequencing data indicate frequent PIK3CA H1047R and TERT promoter mutations, with no significant copy number variations, suggesting a distinct molecular pathogenesis compared to other metaplastic carcinomas." (PMID 41301002, 2025).
cancer (continued). "It is also interesting to note that in the previous experiments generalizing from TCGA to CCLE, we used PIK3CA as an example of a gene where the smallest good model performs best and NF1 as an example where the best model was selected, and this tendency was reversed for these two cancer types." (PMID 39776849, 2024). "Therefore, no clinical trials have been conducted with pan-cancer vaccines targeting the PIK3CA gene." (PMID 38671743, 2024). "Interestingly, we observed increased activities of glycolysis, TCA cycles, oxidative phosphorylation, and fructose and mannose metabolism in the PIK3CA-E542K and PIK3CA-E542K/c-MYC groups, suggesting metabolic reprogramming occurred during the PI3KCA-driven cancer progression." (PMID 39336111, 2024). "Recent investigations have reported that PIK3CA mutations modulate SIRT4 expression through negative regulation of the epigenetic factor EP300, ultimately influencing GPT1 and altering glutamine metabolism in cancer." (PMID 38459595, 2024). "Hence, CARNIVAL was able to construct a signalling network highly enriched for HER2 signalling, including the signalling proteins MAPKs, ESR1, ERBB2, EGFR, PIK3CA and EP300, which are known to be relevant for the primary mechanism of action of lapatinib in HER2 + cancers." (PMID 37715141, 2023). "Notably, of the eight cancer-related genes, six (TSC1, TSC2, PIK3CA, IGF1R, PDPK1 and AKT2) are known longevity related genes according to GenAge database in human/model organisms, and genetic manipulation of these genes can directly lead to shortening or extending lifespan of model organisms." (PMID 37582720, 2023). "A PDX cancer mouse model study showed that resistance to CDK4/6 inhibitors could be alleviated by adding PI3K inhibitors, regardless of PIK3CA mutation." (PMID 36978140, 2023). "Of note, the PIK3CA methylation made no sense in most cancers." (PMID 36211436, 2022). "The cancer target PDB ID 1RY0 (AKR1C3) showed the highest interactions with the majority of the NCs, followed by 1HFQ (DHFR), 3ZGC (NFE2L2), 4AF3 (AURKB), 4K33 (FGFR3), 5P21 (HRAS), 2I0V (CSF1R), and 3ZIM (PIK3CA) protein targets and least interaction was found with the 1M9Z (TGFBR2) protein." (PMID 36387366, 2022). "Moreover, around 27% of the noncanonical mutations characterized in TCGA are unique to HNSCC and have not been identified in other cancers with PIK3CA alterations." (PMID 35887235, 2022). "The finding that both PIK3CA and FBXW7 mutations are both enriched in pre-treatment biopsies and found in post-treatment specimens from cancers that do not respond to neoadjuvant therapy means that they may act as biomarkers for lack of response." (PMID 34256782, 2021). "Given the myriad of signaling pathways affected by PIK3CA, which include both AKT-dependent and -independent mechanisms, there is a need to phenotypically characterize the oncogenic readouts of non-hotspot mutations in more cancer hallmarks." (PMID 32365913, 2020). "The absence of PIK3CA mutations and presence of CNAs in IDP could be used clinically to identify patients at high risk of progression to carcinoma." (PMID 32195332, 2020). "In addition, studies concentrating on somatic mutations in PIK3CA and AKT1 in pure IDP and later carcinomas lacked CNA data." (PMID 32195332, 2020).
cancer (continued). "With regards to known cancer drivers, 24 showed alterations, including the oral cell lineage transcription factors TP63 (amplified, 21.94%) and SOX2 (amplified, 20.97%), CDKN2A, CCND1 (amplified, 24.27%), PIK3CA (amplified, 20.97%) and EGFR (amplified, 10.67%)." (PMID 31703248, 2019). "As the interactome could reveal the interaction among the different genes, we performed network analysis and found that PIK3CA and PTEN could strongly interact and this was consistent with our data as it co-occurred significantly in pan-cancer cell lines and tumors." (PMID 31289610, 2019). "No drugs aimed specifically at cancers with PIK3CA mutations have been approved by the FDA to date, although several PI3K agents targeting the PIK3CA gene product, targeting PI3Kα, have entered into Phase 1 clinical trials including BYL719 (Novartis) and GDC-0032 (Genentech)." (PMID 28806782, 2017). "In addition, MSI cases were characterized by accumulation of mutations in PIK3CA, ERBB3, HER2, and epidermal growth factor receptor (EGFR), but MSI cancers generally lacked targetable amplifications." (PMID 27233623, 2016). "However, mutual exclusivity between NOTCH1 and PIK3CA, which was identified as SMGs via genomic analyses of ESCC patients, has not previously been implicated in any type of cancer." (PMID 26528858, 2016). "The genes MAPK3, HMGB1, HMGA1, PIK3CA, and MCL1 are genes known to stimulate cellular growth; however, contrary to what is normally reported in humans, in the present study these genes were shown to be consistently expressed at lower levels in malignant tumors." (PMID 27657059, 2016). "Subgroup analysis of AKT phosphorylation in tumors without PIK3CA mutations (18 CCC and 12 EC) showed statistically significant increases in both pAKT-Ser473 and pAKT-Thr308 for 8 cancers lacking BAF250a expression on IHC (p = 0.05 and 0.008 respectively; t-test)." (PMID 24559118, 2014). "As robust cell death induction in transformed cells is crucial for effective TRAIL-based anti-cancer therapy, we concluded that interfering with the PI3K/Akt signaling axis or CDKs is most probably insufficient to fully exploit the therapeutic potential of TRAIL in PIK3CA-mutant CRC cells." (PMID 25501831, 2014). "Although PIK3CA mutation was not correlated with patient outcome in this cohort, it was independently associated with worse overall survival in the ESCC patients with family cancer history." (PMID 25054828, 2014). "Given the goal of this study to measure the effect of rapamycin on pre-existing colon cancers with a dominantly active PI3K, we placed into our therapeutic study 22 FC PIK3ca* mice at 55 days of age, an age when most have pre-existing cancer, but have not yet become moribund." (PMID 23593290, 2013). "In this study we also observed that PIK3CA codon 545 substitutions account for 9.8% of PIK3CA mutations in CRC and, since the carcinoma carrying the PIK3CA p.Glu545Asp mutation did not present mutations in either KRAS or BRAF, it is conceivable that this mutation confers some selective advantage." (PMID 23548132, 2013). "Despite suggestions that cancer cells are adept at utilizing other nutrient sources, this study has demonstrated that PIK3CA mutant cells are not readily able to compensate for glucose withdrawal, either through use of glutamine, alternative monosaccharides or other nutrients." (PMID 23028762, 2012). "This phenomenon was somewhat supported by a recent study which found that BRAF mutations represented early events in thyroid carcinogenesis, whereas mutations of PIK3CA and AKT1 were latter events not found in the primary cancers, but in metastases or recurrent cancers." (PMID 22007340, 2012).
cancer (continued). "Hence, PIK3CA and/or the PI3-kinase/PKB/AKT pathway may provide suitable targets for therapeutic intervention in patients with HPV-induced carcinomas." (PMID 21663621, 2011). "Previous studies have revealed higher prevalence of PIK3CA copy gain in ATC (42%) in comparison with FTC (28%), which may indicate that PIK3CA gene participates in the progression of FTC toward more aggressive types of cancer." (PMID 20804548, 2010). "During the comprehensive analysis including all cancer types, the chi‐square test did not demonstrate a significant difference in the prevalence of PTEN mutations between patients with a single PIK3CA mutation (36 of 425 cases) and those with multiple PIK3CA mutations (6 of 49 cases)." (PMID 39054873, 2024). "Genetically engineered mouse models have shown that the combinations with Pten ablation with mutations of Pik3ca, Arid1a, or KrasG12D promote and aggressively develop invasive endometrial carcinomas, whereas solely PTEN loss does not or takes a long time to induce malignant tumors." (PMID 35203298, 2022). "Although not high rate of PIK3CA activating mutations, immunohistochemical evaluation of downstream PIK3CA targets EIF4E and 4E-BP1 suggests that additional mechanisms may play positively regulation in mTOR pathway in cancers." (PMID 30682771, 2019). "The genetic alterations in the three overlapping genes (MAP2K1, PIK3CA and RAF1) revealed by the Damnacanthus indicus C.F.Gaertn prick-related rap1 signal further explored and assessed for the beneficial effects which Damnacanthus indicus C.F.Gaertn may exerts in the treatment of various cancers." (PMID 30906409, 2019). "Moreover, PIK3CA’s role in cancer immune surveillance has not been studied." (PMID 31112530, 2019). "Finally, we also reviewed PIK3CA, CTNNB1, and ARID1A, as well as KRAS and BRAF, for somatic mutations in these genes have been reported to occur in EOC subtypes and corresponding cell lines most often representing other non-HGS subtype cancers." (PMID 26622941, 2015). "Furthermore, in cancer cell lines with mutations in both KRAS and PIK3CA, MEK inhibitor could not induce the cell cycle arrest due to the sustained cyclin D1 expression." (PMID 26121043, 2015). "However, unlike type I cancers (such as clear cell or low-grade endometrioid cancers, which exhibit mutations in PTEN and PIK3CA), the pathway alterations in HGSCs are characterized by deletions (PTEN) and amplifications (PIK3CA, KRAS, and AKT1/2)." (PMID 27231561, 2015). "Furthermore, increased signalling mediated by the PI3K/AKT pathway, achieved via mutations in PIK3CA or loss of PTEN expression are not mutually exclusive, suggesting that independent growth advantages are provided by these two cancer promoting changes in colorectal cancer." (PMID 21473780, 2011). "Recently, several studies have identified that somatic driver mutations that are thought to contribute to EC pathogenesis, including PIK3CA, KRAS and PIK3R1, can exist in normal uteri without cancer." (PMID 36424602, 2022).